TET2 (tet methylcytosine dioxygenase 2)
Diseases named in the same sentence as TET2 in open-access papers (continued):
Sharing a sentence is not in itself a finding about the gene and the disease.
diabetes (continued). "In diabetes, the binding of both Dnmt1 and Tet2 is increased at its promoter, suggesting an active methylation-hydroxymethylation process of the Rac1 promoter." (PMID 31277234, 2019). "They found that peripheral blood mononuclear cells (PBMCs) from patients with diabetes have lower levels of pAMPK, TET2pS99 and TET2 than healthy donors." (PMID 31164154, 2019). "Hyperglycemia acts to downregulate TET2 stability and activity in endothelial cells, but the relevance of this to endothelial dysfunction in diabetes remains unclear." (PMID 40716745, 2025). "Notably, TETs are activated in the retina and retinal vasculature of patients with diabetes, with tet methylcytosine dioxygenase 2 (TET2) emerging as the prominent isoform." (PMID 38172938, 2024). "Glucose-regulated phosphorylation of TET2 by AMPK reveals a pathway linking diabetes to cancer." (PMID 35480097, 2022). "Tet2-KO mice that receive WT bone marrow transplants develop insulitis but not diabetes and islet infiltrates do not eliminate β cells even though immune cells from the mice can transfer diabetes to NOD/scid recipients." (PMID 34417463, 2021). "Tet2 expression is increased during the progression of diabetes in islet cells and in β cells." (PMID 34417463, 2021). "TET2 (ten-eleven translocation-2) and DNMT3A (DNA methyltransferase 3A) are known to cause abnormalities in hematopoiesis, including in the monocyte-macrophage lineage, derangements of which are also seen in atherosclerotic disease and diabetes." (PMID 29181334, 2017). "Intriguingly, a clinical investigation study revealed that TET2 mutations occur more frequently in the diabetes mellitus (DM) group than the non-DM, suggesting a potential connection between TET2 and insulin resistance." (PMID 40459008, 2025). "Metformin, a diabetes drug that promotes AMPK activation, slows growth of xenografted tumors in a TET2-dependent manner." (PMID 34109280, 2021). "The expression of TET3 (but not TET1 and TET2) mRNA was significantly increased in skeletal muscle tissues of humans with diabetes as compared with non-diabetic control counterparts." (PMID 38216792, 2024). "The Tet2-KO NOD mice did not develop spontaneous diabetes whereas the median time to diabetes was 17 and 23 weeks in their WT and HET littermates." (PMID 34417463, 2021). "From a biological perspective, mutations involved with leukemogenesis (DNMT3A, TET2, and ASXL1) are also enriched in patients with diabetes and atherosclerotic disease but without cancer." (PMID 33709085, 2020). "Moreover, TET2 can regulate the expression of ROBO4 and its downstream proteins through active demethylation of the ROBO4 promoter, thereby accelerating the development of retinal vasculopathy in diabetes." (PMID 38172938, 2024). "Similarly, reinstitution of good control after 3 months of poor control in rats did not reverse diabetes-induced increase in retinal Dnmt1 and Tet2, and alter the methylation status of mtDNA and MMP-9." (PMID 27787562, 2016). "In order to further investigate the effect of TET2 on the upregulation of the Txnip in diabetic mice DRG neurons, we used HG (25 mM glucose without insulin) to culture DRG cells to mimic diabetes in vitro." (PMID 36527131, 2022).
heart failure (30 papers, 2019 to 2026). Inability of the heart to pump blood at an adequate rate to meet tissue metabolic requirements. "The presence of common CHIP variants DNMT3 A and TET2 is significantly associated with an increased risk of mortality combined with heart failure hospitalization (HR, 2.1; 95% CI, 1.1–4.0; p = 0.02), independent of traditional cardiovascular risk factors." (PMID 40214958, 2025). "MCC950 was also able to repress IL1B expression in white adipose tissue and subsequent insulin resistance, as well as prevent heart failure in TET-2 deficient mouse models." (PMID 39988580, 2025). "We primarily focused on the two most common CHIP‐driver mutations, DNMT3A and TET2, for which a prognostic role in heart failure is firmly established." (PMID 40702883, 2025). "Specifically TET2 mutations also associate with incident heart failure with preserved ejection fraction (HFpEF), as just recently reported." (PMID 40702883, 2025). "Another study also reported that CHIP with DNMT3A or TET2 mutations was associated with about two times higher risk of death combined with heart failure hospitalization in chronic heart failure of ischemic origin." (PMID 36807865, 2023). "In a murine heart failure model, Tet2 deficiency negatively affected cardiac remodeling and increased pro-inflammatory interleukin (IL)-1β." (PMID 36835370, 2023). "The atheroprotective effect of NLRP3 inflammasome inhibitors, as well as their protection against the development of heart failure in TET2-deficient mice, supports these findings." (PMID 35657494, 2022). "The in vivo study also had shown that Tet2 deficiency in hematopoietic cells is associated with greater cardiac dysfunction in murine models of heart failure as a result of elevated IL-1β signaling." (PMID 32377298, 2020). "Depletion of Tet2 in blood cells was shown to worsen cardiac remodeling and function in two experimental murine models of heart failure, implicating a causative role of Il-1β overproduction in this process." (PMID 33114351, 2020). "In another study, somatic TET2 or DNMT3A variants in individuals with chronic ischemic heart disease appeared to associate with worse long-term clinical outcome due to heart failure." (PMID 31963585, 2020). "In addition, mutations in TET2 or DNMT3A have demonstrated a profoundly increased mortality driven by the progression of heart failure." (PMID 38985383, 2024). "Furthermore, in murine models of heart failure with TET2 deficiency in hematopoietic cells, cardiac function worsened due to the elevation of IL-1β/NLRP3 inflammasome, and the models responded better to IL-1β/NLRP3 inflammasome inhibition." (PMID 37928907, 2023). "Individuals with TET2-mediated clonal hematopoiesis may have greater risk of developing heart failure and respond better to IL-1β–NLRP3 inflammasome inhibition." (PMID 32377298, 2020). "Furthermore, in a murine model of heart failure, TET2 deficiency-associated cardiac dysfunction was associated with a corresponding increase in IL-1β levels." (PMID 31357404, 2019). "The presence of somatic mutations within TET2 or DNMT3A remained independently associated with adverse outcome (death or death combined with heart failure hospitalization) in addition to age, whereas hypertension was not independently associated in this multivariable model." (PMID 30566180, 2019). "Interestingly, in experimental mice harboring Tet2 deletion, myeloid Tet2 deficiency accelerated heart failure through the IL-1β/NLRP3 inflammasome." (PMID 31032261, 2019). "Interestingly, in this study treatment with MCC950, a selective NLRP3 inhibitor, protected against the development of heart failure in TET2-deficient mice." (PMID 31357404, 2019). "Furthermore, DNMT3A or TET2 mutations were associated with accelerated progression of heart failure (further reduction of left ventricular ejection fraction (LVEF), heart failure-related death or hospitalization) within a 3.5 years’ follow-up irrespective of ischemic/non-ischemic etiology." (PMID 35885518, 2022).
heart failure (continued). "Similarly, in experimental heart failure mouse models, hematopoietic Tet2 deficiency followed by competitive transfer or myeloid-specific Tet2 deficiency resulted in severely impaired cardiac remodeling, accompanied by an NLRP3 inflammasome-dependent increase in IL-1β." (PMID 33520997, 2020). "The mechanism by which clonal hematopoiesis of TET2 and DNMT3A exacerbates atherosclerosis and heart failure is proposed to be that mutated macrophages become pro-inflammatory, leading to the growth of arterial plaques and myocardial damage." (PMID 38985383, 2024). "In mouse models of heart failure with hematopoietic or myeloid TET2 deficiency, IL-1β/NLRP3 inflammasome inhibitor ameliorated heart failure." (PMID 37928907, 2023). "The underlying mechanisms by which CHIP and its mutations in ASXL1, DNMT3A, TET2, or JAK2 are related to heart failure development and progression are not well understood." (PMID 35657494, 2022). "This is likely caused by the influence of TET2 deficiency on the IL-1β/NLRP3 inflammatory pathway, as treatment with an NLRP3 inflammation inhibitor protected against the development of heart failure." (PMID 35872888, 2022). "The results showed that Tet2 mutations within hematopoietic cells exaggerate heart failure in Tet2-deficient but not in wild-type mice." (PMID 37123477, 2023). "We investigated how statin therapy relates to TET1, TET2 and TET3 expression in circulating immune cells in heart failure with reduced ejection fraction (HFrEF)." (PMID 42193073, 2026). "Recently, mutations in the two most commonly affected genes, DNMT3 A and TET2, were shown to increase mortality at the low-level VAF of 1.15% and 0.73% in a heart failure cohort." (PMID 40214958, 2025). "Importantly, when a bone marrow transplantation with Tet2‐deficient hematopoietic stem cells was performed that led to Tet2 CHIP, without using any trigger or conditioning to induce heart failure, HFrEF still developed." (PMID 37489738, 2023). "Interestingly, mutations of ASXL1, TET2, and JAK2, but not DNMT3A were found to be a risk factor for heart failure in this study." (PMID 35885518, 2022).
T-cell lymphomas (30 papers, 2013 to 2025). "In the broader context of T-cell lymphomas, TET2 mutations were identified in 53% of PTCLs and were associated with adverse clinical features, including advanced stage and poor prognosis." (PMID 41008827, 2025). "Between 10% and 60% of polyclonal B cells in AITL lymph nodes carry the same TET2 mutation in their corresponding T-cell lymphoma clones." (PMID 36428791, 2022). "More recently, TET2 mutations have been frequently observed in T-cell lymphomas, particularly in AITL and other lymphomas with a TFH-cell phenotype." (PMID 36428791, 2022). "It is believed that DNMT3A mutations arise in hematopoietic progenitor stem cells, upstream of T-cell lineage commitment based on the observation of identical DNMT3A and TET2 mutations in tumor and normal cells in T-cell lymphoma patients." (PMID 33801781, 2021). "Tet2-deficient mouse models elicit altered T-cell differentiation and can develop T-cell lymphoma with TFH-like features." (PMID 29148847, 2018). "In a study of human T-cell lymphoma, simultaneous mutation of TET2 and DNMT3A was detected and DNMT3A mutation precedes TET2 mutation." (PMID 27183914, 2016). "In addition, DNMT3A and TET2 mutations occur concurrently in human malignancies such as T cell lymphoma." (PMID 34039392, 2021). "Interestingly, it has been observed that phenotypically unrelated cancers such as T cell lymphomas of the angioimmunoblastic subtype and MPNs share some genetic markers such as TET2 and DNMT3a mutations that are usually considered myeloid." (PMID 33092233, 2020). "In one case of NLPHL with slightly atypical and expanded intranodular T-cells, the detection of a classic RHOA and TET2 mutation provided definitive evidence of an associated T-cell lymphoma (which could be classified as nodal T-cell lymphoma with TFH-phenotype)." (PMID 37664054, 2023). "Surveying the genomic landscape of reported CAR+ T-cell lymphomas, TET2 LOF aberrations emerge as a recurrent feature, detected in four of seven examined cases involving a commercial CAR-T product." (PMID 40195525, 2025). "Genetic mutations, including DNMT3A and TET2, involved in clonal hematopoiesis, have been identified in both DLBCL and secondary T cell lymphoma." (PMID 41117994, 2025). "TET2 depletion in gene trap mice led to T-cell lymphomas with Tfh features after a long latency (median ~67 weeks)." (PMID 36675240, 2023). "This case provided evidence for a divergent evolution of two clonally-unrelated T-cell lymphomas (cPTCL-NOS and AITL) originating from a common progenitor, which shared the same mutations in TET2 and DNMT3A." (PMID 37646869, 2023). "Mutations of TET2, RHOA (which induces THF lineage specification and promotes T-cell lymphomas in cooperation with loss of TET2), DNMT3A, and IDH2 are also detected." (PMID 36291756, 2022). "It is conceivable that certain TET2 or DNMT3A mutations are stronger drivers that can result in more expanded CH and/or higher efficient T-cell lymphoma development." (PMID 34581268, 2021). "Mutations in Tet methylcytosine dioxygenase 2 (TET2) and DNA methyltransferase 3α (DNMT3A) affecting DNA methylation are frequently found in T cell lymphoma." (PMID 29200404, 2018). "TET2 and NPM1 mutations are markedly associated with DNMT3A mutations in T-cell lymphoma and adult AML, respectively." (PMID 23946816, 2013). "Similarly, hypomethylating agents have been explored in T-cell lymphomas with a TFH phenotype given the known efficacy of this mechanism in myeloid disorders enriched for mutations in TET2 and DNMT3A, mutations that are similarly frequent in T-cell lymphomas with a TFH phenotype." (PMID 36765544, 2023).
T-cell lymphomas (continued). "The T-cell lymphoma panel showed no mutations in RHOA, TET2, DNMT3A, IDH2, and other genes typically altered in TFH-derived and other T-cell lymphomas in both lymph node and BM specimens, further supporting the diagnosis of NMZL." (PMID 41515931, 2025).
lung carcinoma (25 papers, 2014 to 2026). "Although there is a clear role for TET2 loss in the development and progression of some lung cancers, considerably more research is required in this area to fully elucidate the impact of TET2 mutations in this setting." (PMID 40116537, 2025). "Although driver mutations of TETs are infrequent in lung cancer, with TET2 having a higher frequency of somatic mutations compared to TET1 and TET3, an altered expression of TETs has been observed." (PMID 35205708, 2022). "The direct mechanism by which TET2 loss contributes to lung cancer progression is unknown; however, TET2 is recognized as a tumor suppressor in non‐small‐cell lung cancer (NSCLC)." (PMID 40116537, 2025). "Building upon our previous findings, which identified PRC1 as a risk factor in lung cancer with low DNA methylation level, this study demonstrates that TET2 is responsible for the demethylation and transcriptional activation of PRC1 in NSCLC cells by interacting with BACH1." (PMID 40665337, 2025). "TET2 is a methylcytosine dioxygenase that modulates the hematopoietic stem cell expansion and function by controlling DNA methylation, and Tet2-deficient mice show an increased tumor vasculature model of lung cancer." (PMID 38002256, 2023). "To investigate how CPS1 influences TET2-mediated demethylation in metastatic cells, we performed metabolomic analysis on primary (L0) and metastatic (L2 and L6) lung cancer cells." (PMID 41356199, 2026). "This suggests that elevated CPS1 activity drives lung cancer metastasis by accumulating fumarate to mediate the TET2 activity, miR200a DNA methylation and the EMT program." (PMID 41356199, 2026). "While transwell assay showed that overexpression of CPS1 in primary lung cancer cells (L0) led to increased cell migration, vitamin C (VC), known to activate DNA demethylases like TET2 29, dramatically rescued this effect." (PMID 41356199, 2026). "Unlike our study, they found that mutations in ASXL1 exhibited a higher risk of lung cancer than DNMT3A and TET2." (PMID 40679991, 2025). "CHIP (particularly in DNMT3A, TET2, and ASXL1 genes, with VAFs > 10%) associates with a 36% risk increase for lung cancer across several cohorts, even when controlling for other confounders." (PMID 40517440, 2025). "Previous studies have identified specific CHIP mutations, such as those in TET2, JAK2 and AXSL1, as drivers of risk for diseases like acute kidney injury and lung cancer." (PMID 40679991, 2025). "In this study, we demonstrate that TET2-mediated DNA hydroxymethylation inhibits the proliferation and metastasis of lung cancer cells in vitro and in vivo." (PMID 37667220, 2023). "Immunohistochemical staining and quantitative analysis of the data showed that TET2 protein levels were clearly lower in human lung cancer tissues than in normal adjacent lung tissues (P < 0.01)." (PMID 37667220, 2023). "Mechanistically, activation of the cGAS-STING signalling pathway is critical for TET2-mediated suppression of the tumorigenesis and metastasis of lung cancer cells." (PMID 37667220, 2023). "Previous studies have shown that IDH‐mutant proteins can inhibit TET2 activity, while TET2 knockdown confers resistance to EGFR inhibitors in lung cancer cells." (PMID 35526267, 2022). "To identify the contribution of cGAS-STING signalling to the TET2-medicated inhibition of lung cancer cell proliferation, migration and invasion, we then treated the vector control and TET2-overexpressing A549 and H1975 cell lines with the cGAS-STING signalling inhibitor RU.521 (10 μM)." (PMID 37667220, 2023). "Moreover, the prognostic correlation between the 5-hmC/TET2 levels and survival in lung cancer patients was analysed." (PMID 37667220, 2023). "In this study, CPS1 is highly expressed in metastatic lung cancer cells and elevated CPS1 activity accumulates urea cycle-derived fumarate to inhibit TET2 activity, which regulates miR200a-EMT axis in tumor metastasis and reduces PD-L1 in tumor immunity." (PMID 41356199, 2026).
lung carcinoma (continued). "In another study, lung cancer vesicular miR-210 activated the JAK2/STAT3 pathway, and ten-eleven translocation 2 (TET2) promoted the transformation of NFs into CAF." (PMID 36612080, 2022). "To further investigate the effect of TET2-mediated SGK1 demethylation in vivo, we constructed a mouse subcutaneous lung cancer model and randomly divided the mice into two groups: siNC-MDSC (MDSCs transfected with siNC) and siTET2-MDSCs (MDSCs transfected with siTET2-MDSCs)." (PMID 40917754, 2025). "To further confirm the critical role of cGAS-STING signalling in TET2-mediated inhibition of lung cancer cell proliferation and metastasis in vivo, we generated a subcutaneous xenograft model in BALB/c NOD mice (n = 5 group) using vector control and TET2 overexpression cells." (PMID 37667220, 2023). "However, the expression changes in TETs, especially for TET2 and TET3, in lung cancer remain somewhat unclear, with conflicting observations for TET1 in cell lines and primary tumor models." (PMID 35205708, 2022). "Lung cancer-derived exosomal miR-210 was indeed reported to elevate the expression of proangiogenic factors, such as MMP9, FGF2 and vascular endothelial growth factor (VEGF), in recipient fibroblasts by modulating JAK2/STAT3 signaling pathway and ten-eleven translocation 2 (TET2)." (PMID 33572359, 2021).